SRSF1 (serine and arginine rich splicing factor 1)
Diseases named in the same sentence as SRSF1 in open-access papers (continued):
Sharing a sentence is not in itself a finding about the gene and the disease.
tumor (continued). "Research has indicated that SRSF1 plays a significant role in SCLC tumorigenicity and may control tumor progression by influencing DNA damage and chemotherapy sensitivity." (PMID 40129567, 2025). "Furthermore, EBNA1 interacts with the splicing factor SRSF1 to regulate the alternative splicing of SRRM1 and promote tumor development in vitro and in vivo." (PMID 40729735, 2025). "Additionally, HE and IHC staining on in situ xenograft tumor specimens were conducted and the morphological characteristics of the circCMTM3/STAT5A/SRSF1 feedback loop were identified." (PMID 39310105, 2024). "Furthermore, SRSF1 activates alternative splicing of Numb, an inhibitor of the NOTCH signaling pathway, thereby augmenting NOTCH signaling and promoting tumor growth and progression." (PMID 38735973, 2024). "This weakens ASE of PTK2 mediated by SRSF1 (the effector of SRSF1 carcinogenic activity), leading to a decrease in PTK2 mRNA and protein expression, and thereby inhibiting cell proliferation, migration, and survival in tumor progression." (PMID 38302461, 2024). "Notably, patients with a high SRSF1 expression presented a lower ESTIMATE score, immune score, and stromal score (all p < 0.05) and a higher level of tumor purity(p < 0.05)." (PMID 37206090, 2023). "Interestingly, 16 of the 34 components examined (47.1%) were altered and, in line with our Discovery cohort, KHDRBS1, NOVA1, PRPF8, SNW1, SRSF1, and SRSF9 were also overexpressed in tumor tissue in this external cohort." (PMID 38049848, 2023). "We also investigated whether overexpression of SR (Serine/arginine) protein SRSF1 (previously known as SF2/ASF) drives aberrant AS in MM, thus impacting tumor growth and survival, which provides important biological insights with translational potential." (PMID 36535935, 2022). "The expression of SRSF1 in Her2 and luminal A subtypes is not consistent with the result of the GEO profile analysis, and it was highly expressed in tumor tissues rather than normal tissues." (PMID 36313438, 2022). "Crucially, partial genetic downregulation of Srsf1 does not detrimentally affect normal tissue homeostasis, demonstrating that tumour cell plasticity can be differentially targeted." (PMID 35589755, 2022). "In addition, SRSF1 and SRSF3 were found mutually dependent and co-expressed in normal and tumor tissues/cells." (PMID 35463320, 2022). "RT-qPCR and immunoblotting data showed that SRSF1 was upregulated in tumor tissues compared with adjacent nontumorous tissues on both RNA and protein levels." (PMID 33602301, 2021). "Finally, the tumor-related role of SRPK1/2, SRSF1, Mnk2b, and PP1α were validated in CAC cell lines as well as in xenograft models." (PMID 33602301, 2021). "Moreover, SRSF1 was positively correlated with malignant BRCA features, including the Ki-67 index and histological tumor grade in BRCA and poor prognosis in HR+ BRCA patients." (PMID 33992102, 2021). "Considering the biological function of SRSF1 in tumor cells, we investigated whether PTPMT1-L could partially mediate the oncogenic effects of SRSF1." (PMID 33992102, 2021). "No statistical difference was observed between tumor tissues and adjacent tissues regarding to cytoplasm-SRSF1." (PMID 33602301, 2021). "Nuclear expression of Srsf1 was detectable in the endothelium of various tumor types, but not in healthy tissues." (PMID 30641926, 2019). "Collectively, our data show circSMARCA5 as a promising druggable tumor suppressor in GBM and suggest that it may exert its function by tethering the RBP SRSF1." (PMID 29415469, 2018). "VEGFxxxb mRNA and protein were undetectable in 786-O cells, hence we hypothesized that SRSF1 down-regulation should decrease tumor growth by increasing the VEGFxxxb/VEGF ratio and thus by inhibiting tumor vascularization." (PMID 27999187, 2017).
tumor (continued). "Overexpressing SRSF1 confers OXA resistance to EOGC cells, promotes colony formation, and inhibits apoptosis, and it could promote exon skipping in downstream genes, thereby altering tumor-related functions." (PMID 41690589, 2026). "However, the impact of SRSF1 on tumor growth through non-cell or cell-autonomous effects on CD8+ T cell function is not yet fully understood." (PMID 39837814, 2025). "Similar with the in vitro results, the analysis by xenograft tumor model suggested that CYT notably reduced the tumor size and growth curve of MDA-MB-231-DR cells, along with decreased level of KI-67, whereas overexpression of SRSF1 and MYO1B reversed these effects." (PMID 40176901, 2025). "Furthermore, knockdown of SRSF1 or overexpression of miR-6760-5p mimics did not affect tumor sphere formation in GSC11 or GBM1 cells." (PMID 37063420, 2023). "For example, SRSF1 regulates the alternative splicing of the tumor suppressor BIN1, which interacts with the proto-oncogene MYC to inhibit its proliferative activity, while SRSF1 overexpression endorses BIN1 exon12a inclusion that lacks tumor-suppressor activity due to reduced binding with MYC." (PMID 35027535, 2022). "In line with previous findings in vitro, GSCAR knockdown markedly inhibited tumor growth in vivo, as evidenced by the decreased Ki67 and increased cleaved caspase 3 (CC3) immunohistochemical (IHC) staining signals, which could be overcome by SRSF1 overexpression." (PMID 37063420, 2023). "Conversely, application of a similar approach using various methods and antibodies did not reveal consistent differences in the signal abundance and intensity for SRSF1 and SRSF9 in tumor vs. non-tumor tissue." (PMID 38049848, 2023). "SRSF1 mRNA levels were unaltered upon siRNA or drug inhibition of SRPK1 in HPV-infected keratinocytes (data not shown), suggesting that SRSF1 may undergo proteasomal degradation in the cytoplasm of SRPK1-depleted, or inhibited, non-tumour keratinocytes." (PMID 32182205, 2020).
infection (24 papers, 2008 to 2025). The state of being infected such as from the introduction of a foreign agent such as serum, vaccine, antigenic substance or organism. "Increased R-loop formation upon infection will be required, with particular attention to host encoded transcripts enriched in SRSF1 and RNPS1 binding site clusters." (PMID 33299552, 2020). "Nevertheless, our data suggest that there was a defective naive and effector CD8 T cell migration in the Srsf1-cKO mice post infection." (PMID 36189299, 2022). "The increasing amount of SRSF1 bound to the viral genome as the infection progresses, is a clear indication of its role in viral RNA processing." (PMID 34930105, 2021). "The efficiency of in vivo adenoviral gene transfer of SRSF1 was confirmed by western blot 4 days after infection." (PMID 28799539, 2017). "Interestingly, we observed higher frequencies of naive (CD44loCD62Lhi) CD8 T cells and a lower frequency of the effector (CD44hiCD62Llo) CD8 T cells in the spleen of the Srsf1-cKO mice post infection." (PMID 36189299, 2022). "Furthermore, SRSF1 also binds to the NCCR to inhibit transcription of both early and late viral genes, including T-antigen, and suppression of SRSF1 in glial cells facilitates their infection by JCV." (PMID 29456537, 2018). "Transduction of human iNPC (induced neural progenitor cells)-differentiated astrocytes (iAstrocytes) using a viral multiplicity of infection (MOI) of 5 led to efficient transcript knockdown comparable to levels achieved in vivo in neuroprotected G4C2x36+SRSF1-RNAi Drosophila." (PMID 28677678, 2017). "We suggest that the mRNA splicing changes observed subsequent to infection of an RNA virus could be a consequence of replicated viral genome binding to RBPs, thus changing the nuclear stoichiometry of splicing proteins (such as SRSF1)." (PMID 33299552, 2020). "This dual-action suppression of JCV gene expression puts SRSF1 in a special position in regulation of JCV reactivation and the viral lytic infection cycle." (PMID 27257867, 2016). "However, another nuclear protein, serine/arginine-rich splicing factor 1 (SRSF1), retained its nuclear localization during SVA infection." (PMID 39207136, 2024). "No direct correlation between ISG induction and SRSF1 repression could be found for the group of chronically HIV-1-infected individuals, which generally represent a heterogeneous cohort due to unmatched infection phases, comorbidities, and other factors." (PMID 36458014, 2022). "These are derived from the number of SRSF1 and RNPS1 sites expressed in either a single A549 cell or a type II primary pneumocyte (cells were not infected; note that infection would be expected to alter the expression profile, which could affect expressed binding site estimates)." (PMID 33299552, 2020).
cardiovascular diseases (3 papers, 2017 to 2024). "Our present study demonstrates that PRMT1 relieves MH by methylating SRSF1, which is expected to provide a new theoretical basis for the pathogenic mechanism of MH and potential drug targets for reducing MH and associated cardiovascular disease." (PMID 39659162, 2024). "In the context of cardiovascular diseases, studies have revealed that SRSF1 knockout mice exhibit aberrant splicing of Ca2+/calmodulin-dependent kinase IIδ in cardiomyocytes, leading to severe defects in myocardial excitation-contraction coupling." (PMID 39578852, 2024). "What is more, SRSF1 deletion inhibits the growth and migration of both human aortic and coronary arterial SMCs, increasing the possibility of its utility as a therapeutic target in cardiovascular diseases." (PMID 28799539, 2017). "Although substantial evidence indicates that aberrant protein selective splicing is related to MH, in which SRSF1 is involved in cardiovascular disease by selectively splicing downstream signaling proteins, whether PRMT1 affects MH by regulating SRSF1 remains largely unknown." (PMID 39659162, 2024). "However, the function and mechanism of SRSF1 in cardiovascular diseases remain unclear." (PMID 39578852, 2024). "Serine/arginine-rich splicing factor 1 (SRSF1) affects the development and progression of cardiovascular disease by selectively splicing downstream signaling proteins." (PMID 39659162, 2024).
genetic diseases (1 paper, 2024). "SRSF1 has been observed to promote nonsense-mediated mRNA decay (NMD) by recruiting UPF1, suggesting its regulatory role in gene expression and genetic diseases." (PMID 38735973, 2024).
hematological malignancies (1 paper, 2023). "Additionally, studies about the role of SRSF1 in normal hemopoiesis and hematological malignancies have been emerging as well." (PMID 37206090, 2023).
inflammation (1 paper, 2025). Aberrant reaction of the microcirculation characterized by movement of fluid and leukocytes from the blood into extravascular tissues. "Another study indicated that SRSF1 participated in lncRNA MAAMT-induced myocardial inflammation by promoting macrophage activation." (PMID 40585977, 2025). "In conclusion, abnormal high expression of SRSF1 facilitated CME-induced cardiac inflammation via promoting NF-κB-mediated transcription and production of inflammatory cytokines." (PMID 40585977, 2025).
metabolic disorders (1 paper, 2024). "Eliminating SRSF1 genetically triggers the whitening of brown adipocyte tissue (BAT) and compromises its thermogenic function, consequently causing metabolic disorders in mice." (PMID 38569495, 2024). "Genetic ablation of SRSF1 results in the whitening of BAT and a reduction in thermogenic function, leading to metabolic disorders in mice." (PMID 38569495, 2024).
SRSF1 also shares sentences with these, for which no sentence is quoted: basal cell carcinoma (2 papers); brain tumor (2); degenerative diseases (2); gastric tumor (2); Insulin resistance (2); neurological diseases (2); osteoarthritis (2); Wilms tumor (2); acute myocardial infarction (1); adenocarcinoma (1); adenovirus infection (1); amyotrophic lateral sclerosis (1); ankylosing spondylitis (1); aplastic anemia (1); astrocytic neoplasms (1); astrocytomas (1); autosomal dominant cerebellar ataxia (1); brain glioblastoma (1); bronchiectasis (1); cervical squamous cell carcinoma (1); cholestasis (1); chondrodysplasia (1); Crohn disease (1); cutaneous squamous cell carcinoma (1); deafness (1); diffuse astrocytoma (1); ductal carcinoma (1); Fanconi anemia (1); fungal infection (1); heart disease (1).
A further 35 diseases each share a sentence with SRSF1 in 1 paper.